RNU2-32P (RNA, U2 small nuclear 32, pseudogene)
Gene: Small nuclear RNA gene on chromosome 17 (41,467,956 to 41,468,146, forward strand). Ensembl gene ENSG00000223125.
Homologues: Orthologues: chimpanzee U2 (100% identical), macaque U2 (94% identical), dog U2 (80% identical), pig U2 (72% identical), mouse Gm23206 (64% identical), rat LOC120098016 (61% identical). Paralogues in human: U2 (85% identical), RNU2-64P (84% identical), U2 (84% identical), RNU2-4P (83% identical), RNU2-59P (83% identical), RNU2-26P (82% identical), RNU2-14P (81% identical), RNU2-2 (81% identical), RNU2-57P (81% identical), RNU2-61P (81% identical), RNU2-23P (80% identical), RNU2-3P (80% identical), and 67 more.